CXCL13 (C-X-C motif chemokine ligand 13)
Diseases named in the same sentence as CXCL13 in open-access papers (continued):
Sharing a sentence is not in itself a finding about the gene and the disease.
COVID-19 (33 papers, 2020 to 2026). A disease caused by infection with severe acute respiratory syndrome coronavirus 2. "Here the authors demonstrate the association of HGF and CXCL13 production with increased severity and mortality in COVID-19 patients." (PMID 34373466, 2021). "In addition, studies have shown that c-reactive protein (CRP), interleukin-6(IL-6), D-dimer and hepatic cytokines (HGF) and C-X-C motif chemokine 13 (CXCL13) are associated with the occurrence of pulmonary fibrosis in patients with COVID-19." (PMID 35069217, 2021). "Furthermore, excessive amounts of CXCL-13 have been associated with worse outcomes in COVID-19." (PMID 39000027, 2024). "HGF and CXCL13 were also previously identified as markers of severe COVID-19 and good predictors of ICU admission." (PMID 38839796, 2024). "The combination HGF/CXCL13 was the best predictor for ICU-admission but also fatal outcome in 3 combined independent cohorts of COVID-19 patients." (PMID 38839796, 2024). "HIV-1-infected and COVID-19 patients have higher levels of plasma and serum CXCL13 concentration, and CXCL13 has been identified as a biological signature of COVID-19 patients and HIV-1 patients." (PMID 38229736, 2024). "We also found the level of plasma CXCL13 from severe COVID-19 patients was significantly higher than mild patients during acute infection." (PMID 37061513, 2023). "However, excessive CXCL13 levels are probably associated with an inadequate immune response that might be associated with severe COVID-19, while the reduced CXCL12 levels in hospitalized patients might be associated with an increased consumption by GC B cells, indicating a massive B cell response." (PMID 36560669, 2022). "CXCL13 has been indicated as a possible biomarker for severe COVID-19, since it has been found highly increased in severe patients, particularly in those who succumbed to the disease." (PMID 34858405, 2021). "Up-regulation of HGF reflects the most powerful counter-regulatory mechanism of the host immune response to antagonize the pro-inflammatory cytokines including CXCL13 and to prevent lung fibrosis in COVID-19 patients." (PMID 34373466, 2021). "In conclusion, the present study provides insights in the early pathophysiological events associated with severe COVID-19 and identified HGF and CXCL13 as critical pathogenic biomarkers of disease severity and best predictors of ICU admission and death." (PMID 34373466, 2021). "We have identified two cytokines, i.e., HGF and CXCL13, as the best immunological signature predicting the severity of COVID-19 requiring ICU admission." (PMID 34373466, 2021). "CXCL13 is a B cell attracting chemokine and while its role in A. baumannii infection is unclear, it has previously been identified as a biomarker for sepsis and a predictor of mortality in COVID-19 patients." (PMID 36054235, 2022). "With regard to CXCL13, the early increase in the symptomatic severe COVID-19 may also reflect the potent host immune response to promote maturation of B cell and antibody response in order to achieve rapid control of the virus replication and virus clearance." (PMID 34373466, 2021). "Our study provides a broad view of the anti-SARS-CoV-2 immune response and reveals that CXCL13 may serve as a novel predictor of lethal infection in COVID-19 patients." (PMID 33472985, 2021). "The data suggest that one of these proteins (CXCL13) may be a novel biomarker for severe COVID-19 that can be readily measured in blood." (PMID 33472985, 2021). "CD27 and increased expression of CXCL13 may support blast response from B cells, as is seen in COVID-19, further propelling vascular inflammation and lung injury." (PMID 34177897, 2021). "Finally, since MAFB-dependent factors like IL-10, SPP1, CCL2, and CXCL13 are biomarkers for COVID-19 severity, we next assessed whether additional MAFB-dependent soluble factors might also predict COVID-19 severity or outcome." (PMID 37917179, 2023).
COVID-19 (continued). "Indeed, knock-down of MAFB prior to SARS-CoV-2 exposure significantly reduces the expression of chemokines that stimulate fibrosis (CXCL13, CCL18) and neutrophil recruitment (various CXCL chemokines), 2 processes that are closely linked to COVID-19 severity and post–COVID-19 pulmonary sequelae." (PMID 37917179, 2023). "Moreover, it has been found that patients with severe COVID-19 produce higher serum levels of CXCL13 and increased frequencies of ASCs and TFH cells, and increased production of the specific antibodies of the RBD of SARS-CoV-2, compared to those with moderate disease." (PMID 35893822, 2022). "Furthermore, a study examining the serum levels of CXCL13 in convalescent COVID-19 at various severities showed that CXCL13 serum levels were elevated significantly in patients with severe COVID-19 compared to those in patients with mild, moderate, or asymptomatic disease." (PMID 35893822, 2022). "Thus, HGF and CXCL13 were the best predictors of COVID-19 severity and ICU admission." (PMID 34373466, 2021). "Some COVID-19 convalescent plasma indicated high levels of IgGs to certain chemokines (for example, CCL8, CXCL13 and CXCL16) compared with healthy controls." (PMID 36879067, 2023). "Cytokine IFNA7, as well as chemokines CXCL13, CXCL10, CCL7, and CCL8 were present in the proteins selected for predicting severe COVID-19." (PMID 37069249, 2023). "HLA-DRB3, CXCL13, PTPN22 and AHR were identified as genes that were commonly down-regulated in both COVID-19(+) TV and COVID-19(+) PU groups compared to the COVID-19(-) PU control group." (PMID 37026002, 2023). "We have shown that, among the 49 soluble mediators measured, two cytokines, HGF and CXCL13, are the best predictors of the need for ICU hospitalization for COVID-19 patients." (PMID 34373466, 2021). "Positive correlations between the serum CXCL13 level and the levels of IL-6 and CXCL10 were also noted in COVID-19 patients." (PMID 32963357, 2020). "Interestingly, a recent study reported that 12 months after infection, patients with mild COVID-19 had higher autoantibody levels to cytokines such as CCL21, CXCL13, and CXCL16, compared to long COVID-19 patients." (PMID 38491326, 2024). "Similar to IL-6, IL-10, and TNF- α, CCL-3 and CXCL-13 levels were not significantly different between mild-to-moderate COVID-19 patients, recovered individuals, and healthy controls." (PMID 38646483, 2024). "Importantly, among the 14 overlapping proteins, those three chemokines, CXCL13, CXCL10, and CCL7 were selected for predicting both severe and critical COVID-19." (PMID 37069249, 2023). "While some genes involved in monocyte and lymphocyte migration and function were expressed in the COVID-19(+) TV group (CCL13, CCL8, and CCL20), a greater number of these genes were expressed in the COVID-19(-) PU control group (CCL19, CCL18, CXCL13, CCL4, CCL5, CXCL9)." (PMID 37026002, 2023). "Three chemokines, CXCL13, CXCL10, and CCL7 were selected for predicting critical COVID-19." (PMID 37069249, 2023). "Conversely, in non-vaccinated COVID-19 patients, increased CXCL13 levels have been shown to be a marker of a poor clinical outcome compared to patients who survived COVID-1929,30." (PMID 35288576, 2022). "In contrast to COVID-19(+) TV, highly expressed in the COVID-19(-) PU control group included MHC class II antigen processing (HLA-DRB3/4, HLA-DPB1, HLA-DRA, CIITA, and CD74), mast cell degranulation (TPSAB1/B2), B cell activation (CXCL13, BLNK, IL-6) and histone modification (USP21, HIST1H4E)." (PMID 37026002, 2023). "In addition, higher CXCL13 sera levels were detected in patients who survived COVID-19 compared to those in patients that did not survive, suggesting that CXL13 sera levels can be used as a novel predictor of the lethality of SARS-CoV-2 infection." (PMID 35893822, 2022). "In addition, as a ligand of CXCR5, CXCL13 was also found at a higher serum level in the severe COVID-19 patients than in the nonsevere patients." (PMID 32963357, 2020).
COVID-19 (continued). "In conclusion, our study demonstrates that BLC/CXCL13, sCD30, MCP-2/CCL8 and IP-10/CXCL10 are specifically and individually upregulated in symptomatic COVID-19-positive patients but not in patients suffering from other respiratory infections with similar symptoms." (PMID 34540715, 2021).
Autoimmunity (26 papers, 2010 to 2025). The occurrence of an immune reaction against the organism's own cells or tissues. "Several investigations regarding CXCL13 and the brain center on its contributions to autoimmunity, with converging findings suggests that CXCL13-mediated recruitment of B cells is associated with disease severity, progression, and poor prognosis (Londoño and Mora, 2018)." (PMID 38650657, 2024). "CXCL-13 (BCA-1), known for its role in B cell chemotaxis and tertiary lymphoid structure formation, has also been implicated in autoimmunity and immunotherapy response." (PMID 41394871, 2025). "First described in SPMS in the early 2000s, these reports of organized niches with prominent CXCL13 expression sustaining CNS inflammation and autoimmunity have directed attention to the role of the meninges in the pathogenesis of MS." (PMID 36078057, 2022). "For one, we did not see systemic differences among the groups, even though previous studies have demonstrated effectiveness in blocking CXCL13 on autoimmunity." (PMID 34868008, 2021). "The clinical relevance of serum CXCL13 in autoimmunity, infection, chronic inflammation and malignancy is widely apprehended and intensely investigated." (PMID 32089130, 2020). "This work describes pre-clinical development of human anti-CXCL13 antibody MAb 5261 and includes therapeutic efficacy data of its mouse counterpart in murine models of autoimmunity." (PMID 25879435, 2015). "We demonstrate that this monoclonal antibody is able to inhibit in vitro functional activity of human and mouse CXCL13 and present efficacy data of its murine analog in murine models of autoimmunity." (PMID 25879435, 2015). "The macrophages are then activated and produce CXCL13, which promotes chemotaxis toward B1 cells and thus leads to the development of autoimmunity." (PMID 20856892, 2010). "Thus CXCL13 controls the segregation of lymphocytes between T and B cell compartments and modulates autoimmunity as it drives germinal centre B cells to the light zone where antigen selection occurs." (PMID 39188767, 2024). "It is necessary to utilize better animal models, human pathological specimens, and in vitro research to further investigate the regulatory role of CXCL13 in ectopic lymphoid neogenesis, immune cell activation and other key pathological processes in autoimmunity." (PMID 35309354, 2022). "Abnormal expression of CXCL13, consistent with that of other chemokines and cytokines, contributes to ectopic lymphoid neogenesis in local lesioned tissues, and promotes the production of autoantibodies in autoimmunity." (PMID 35309354, 2022). "Upregulated BAFF and chemokine (C-X-C motif) ligand 13 (CXCL13, also known as B lymphocyte chemoattractant) occurred as a consequence of over-expressed Vgll3 in females, further implicating it as a driver of sex-specific autoimmunity." (PMID 33183347, 2020). "Recent findings underscore the pivotal role of key cytokines and chemokines – such as IL-17, TNF-α, IL-6, BAFF, and CXCL13 – as well as specific autoantibodies (e.g. ACPA, ANA) that not only drive local inflammation but may also perpetuate systemic autoimmunity in susceptible individuals." (PMID 41257445, 2025). "CXCL13 is a chemokine that enables activated B and T cell migration to the germinal center, and its serum level may be reflective of germinal center formation/activity, while RF is a by-product in autoimmunity of overactive B and T cell costimulation." (PMID 38839899, 2024). "Thus, CXCL13/CXCR5-associated immune activities of SLO involve a gradually discovered arsenal of players contributing to adaptive humoral immunity, their balance being of utmost relevance for infection control and prevention of autoimmunity from top to bottom." (PMID 36078057, 2022). "Given the positive regulation of proinflammatory genes (e.g., IL17, CXCL13, and CSF2) by MIAT, we were interested in investigating the significance of MIAT in autoimmunity." (PMID 35784351, 2022).
Autoimmunity (continued). "This review summarizes the recent advances in our understanding of the CXCL13/CXCR5 immune axis and its role in vaccination, autoimmunity, and infection with a special focus on its relevance for intrathecal B cell activities in inflammatory CNS diseases." (PMID 36078057, 2022). "CXCL13 levels in ESRD, censored for clinical autoimmunity (n = 14; 87 pg/ml; 55–243 pg/ml, P = 0.01), also differed from controls (data not shown)." (PMID 27957330, 2016). "Increased levels of CXCL13 are associated with the development of B-cell lymphomas in the setting of autoimmunity, but we detected no significant change in CXCL13 gene expression in EBLs compared with the control group of DLBCLs." (PMID 41008822, 2025). "The moderately elevated CXCL13 levels, characterizing the ESRD group, were consistent with the general absence of patients with active autoimmunity within this group." (PMID 27957330, 2016).
colon cancer (24 papers, 2014 to 2025). "High numbers of TFH cells and high levels of CXCL13 are associated with increased survival of colon cancer patients." (PMID 34795697, 2021). "The results showed that the expression levels of the ITLN1 and CXCL13 genes in normal tissues were higher than those in colon cancer tissues, and the expression was located in the cytoplasm and cell membrane." (PMID 33579281, 2021). "In this study, we constructed a 6-gene signature (ITLN1, HOXD9, TSPAN11, GPRC5B, TIMP1 and CXCL13) prognostic stratification system based on the colon cancer invasion-related genes, and evaluated the stability and accuracy of the model." (PMID 33579281, 2021). "In colorectal or colon cancer, the CXCL13/CXCR5 axis mediates the pathogenesis, development, and distal metastasis of tumor cells through upregulating the expression and secretion of MMP13, as well as activating the PI3K/Akt pathway." (PMID 34947813, 2021). "According to research, the CXCL13/CXCR5 axis promotes colon cancer incidence, progression, and metastasis by secreting MMP13 and activating the PI3K/AKT pathway." (PMID 34922542, 2021). "CXCL13 mediates distal metastasis of colon cancer by increasing the secretion of MMP13 and the activation of the PI3K/Akt pathway." (PMID 34947813, 2021). "The box plots suggested that the ITLN1, TSPAN11, CPRC5B, and CXCL13 genes were significantly lowly expressed in the colon cancer samples and the TIMP1 gene was highly expressed in the colon cancer samples in the TCGA cohort." (PMID 33579281, 2021). "For C4 (Th17), only nine DEGs, including TNFRSF9 and CXCL13 were screened between colon cancer and rectal cancer." (PMID 33584715, 2020). "As in other cancers, CXCL13 and its receptor also play roles within the immune landscape of colon cancers." (PMID 31354634, 2019). "Direct antitumor effects by CXCL13 were also observed in a colon cancer model." (PMID 35552285, 2022). "CXCL13 and CXCR5 are associated with poor prognosis in advanced colon cancer." (PMID 33579281, 2021). "It has been suggested that the CXCL13 may play a crucial role in the development, metastasis and relapse of advanced colon cancer, and can be used as a prognostic marker for colon cancer." (PMID 34621670, 2021). "Furthermore, when colon cancer cells were endoscopically injected into the colon submucosa, CXCL13 injection reduced tumor formation, whereas the deficiency in CXCR5 gene, a receptor for CXCL13, accentuated tumor formation." (PMID 24966464, 2014). "Such cells include CXCL13+ CD4+ T cells, which have antitumor effects in colon cancer, CXCL13+ CD8+ T cells, and CXCL13+ CD8+ proliferating T cells." (PMID 37091868, 2023). "Et al. reported that colon cancer-derived exosome miR-934 activates the PI3K/AKT pathway to induce macrophage M2 polarization and promote liver metastasis of colon cancer through CXCL13 and other cytokines." (PMID 38105184, 2023). "The PI3K/AKT pathway also plays a key role in the CXCL13/CXCR5 axis, promoting colon cancer growth and invasion." (PMID 34947813, 2021). "From a functional standpoint, CXCL13 induces proliferation and migration in CXCR5-expressing colon cancer cells." (PMID 31354634, 2019). "IL-21 is produced by CXCL13 + CD4 + T cells in human colon cancer, liver cancer, and non-small cell lung cancer." (PMID 38833177, 2024). "The CXCL13/CXCR5 axis promotes tumor progression through the PI3K/AKT/mTOR pathway, contributes to poor prognosis in clear cell renal cell carcinoma, and promotes the growth and invasion of colon cancer cells via the PI3K/AKT pathway." (PMID 33213490, 2020).